IMP4 (IMP U3 small nucleolar ribonucleoprotein 4)
Description:
Component of the 60-80S U3 small nucleolar ribonucleoprotein (U3 snoRNP). Required for the early cleavages during pre-18S ribosomal RNA processing. Part of the small subunit (SSU) processome, first precursor of the small eukaryotic ribosomal subunit. During the assembly of the SSU processome in the nucleolus, many ribosome biogenesis factors, an RNA chaperone and ribosomal proteins associate with the nascent pre-rRNA and work in concert to generate RNA folding, modifications, rearrangements and cleavage as well as targeted degradation of pre-ribosomal RNA by the RNA exosome.
Synonyms: BXDC4; MGC19606
Tractability: Small molecule: a structure with a bound ligand is known. PROTAC: ubiquitination databases record sites on it; its protein half-life has been measured.
Gene: Protein-coding gene on chromosome 2 (130,342,403 to 130,347,967, forward strand). Ensembl gene ENSG00000136718.
Subcellular location: Nucleus, nucleolus
Subcellular location (Human Protein Atlas): Nucleoli
Pathways (Reactome):
Metabolism of RNA: Major pathway of rRNA processing in the nucleolus and cytosol; rRNA modification in the nucleus and cytosol
Gene Ontology:
Molecular function: protein binding; snoRNA binding; rRNA binding; rRNA primary transcript binding
Biological process: ribosomal small subunit biogenesis; maturation of SSU-rRNA; rRNA processing
Cellular component: Mpp10 complex; nucleolus; preribosome; small-subunit processome; nucleoplasm
Genetic constraint (gnomAD): Loss-of-function variants: 28 observed, 36.09 expected, observed/expected ratio (o/e) 0.78, 90% interval 0.57 to 1.06. The upper end of that interval is the gene's LOEUF score, 1.06, which puts it in group 4 of 6, group 1 being the genes least tolerant of losing a copy. Missense variants: 368 observed, 398.28 expected, observed/expected ratio (o/e) 0.92, 90% interval 0.85 to 1.01. Synonymous variants: 162 observed, 159.15 expected, observed/expected ratio (o/e) 1.02, 90% interval 0.89 to 1.16.
Homologues: Orthologues: macaque IMP4 (99% identical), mouse Imp4 (98% identical), rat Imp4 (98% identical), pig IMP4 (96% identical), chimpanzee IMP4 (94% identical), dog IMP4 (93% identical), rabbit IMP4 (88% identical), tropical clawed frog imp4 (79% identical), zebrafish imp4 (77% identical), guinea pig IMP4 (67% identical), Caenorhabditis elegans ZK795.3 (59% identical), Drosophila melanogaster CG11920 (54% identical). Paralogues in human: RPF1 (32% identical).
Diseases named in the same sentence as IMP4 in open-access papers:
IMP4 is named in the same sentence as 10 diseases in open-access papers, as found by Europe PMC text mining. Sharing a sentence is not in itself a finding about the gene and the disease. The quoted sentences say what the papers report.
lung adenocarcinoma (2 papers, 2022 to 2025). A carcinoma that arises from the lung and is characterized by the presence of malignant glandular epithelial cells. "Literature reported increased IMP4 expression in human lung adenocarcinoma (LUAD) tissues, where it promoted disease progression through activation of the ERK pathway." (PMID 39949372, 2025). "Our study aimed to elucidate the function of IMP U3 small nucleolar ribonucleoprotein 4 (IMP4) in lung adenocarcinoma (LUAD) and its potential molecular mechanisms." (PMID 36317123, 2022).
Alzheimer disease (1 paper, 2023). A progressive, neurodegenerative disease characterized by loss of function and death of nerve cells in several areas of the brain leading to loss of cognitive function such as memory and language. "Notably, IMP4’s mRNA expression is significantly lower in Alzheimer’s disease (AD) patients as compared to controls in both temporal cortex (P = 0.003) and prefrontal cortex (P = 2.6 × 10−6), the two most relevant brain regions for AD pathogenesis." (PMID 37189164, 2023).
lung carcinoma (1 paper, 2022). "A previous study showed that IMP4 is highly expressed in human lung cancer and verified it as a new therapeutic target for lung cancer." (PMID 36317123, 2022). "Moreover, IMP4 was shown to be up-regulated and was verified to be a novel target for lung cancer therapy." (PMID 36317123, 2022).
cancer (2 papers, 2025). A tumor composed of atypical neoplastic, often pleomorphic cells that invade other tissues. "However, SUMF2, PTP4A2, and IMP4 are associated with other types of carcinomas." (PMID 41263940, 2025). "The increased expression of hub genes GNL2, RPS23, and IMP4 was not significant in GEPIA, but other studies have reported the increased expression of GNL2, RPS23, and IMP4 in cancer." (PMID 39949372, 2025).
infectious disease (1 paper, 2022). A disorder directly resulting from the presence and activity of a microbial, viral, or parasitic agent in humans. "Additionally, the emergence of metallo-β-lactamases (MBLs) NDM-1 and IMP-4 has also become an established major public health, posing new challenges to the treatment of infectious diseases." (PMID 35711757, 2022).
tumour (1 paper, 2022). "In vivo experiments further verified that IMP4 silencing repressed the growth of subcutaneous tumours and glycolysis." (PMID 36317123, 2022). "In addition, a mouse tumour xenograft model was used to evaluate the role of IMP4 in tumour progression." (PMID 36317123, 2022). "Moreover, H&E staining confirmed that IMP4 silencing decreased the number of LUAD cells in tumours." (PMID 36317123, 2022). "The results revealed that IMP4 silencing reduced the levels of GLUT1, HK2, PFKP, PKM2, and LDHA in LUAD cells and tumour tissues." (PMID 36317123, 2022). "In this study, we demonstrated that IMP4 dramatically increased glucose uptake, lactate generation, and ATP synthesis in LUAD cells and tumour tissues, suggesting that IMP4 could enhance glycolysis in LUAD." (PMID 36317123, 2022). "Meanwhile, knockdown of IMP4 significantly reduced p-MEK and p-ERK expression in xenograft tumours." (PMID 36317123, 2022). "In our study, we demonstrated that IMP4 silencing significantly inhibited proliferation, migration, invasion, and glycolysis; promoted apoptosis; induced cell cycle arrest in LUAD cells; and suppressed tumour growth and glycolysis in a nude mouse xenograft model." (PMID 36317123, 2022).
IMP4 also shares sentences with these, for which no sentence is quoted: infection (1 paper); migraine (1); ulcerative colitis (1); urinary tract infection (1).